IRF8 (interferon regulatory factor 8)
Diseases named in the same sentence as IRF8 in open-access papers (continued):
Sharing a sentence is not in itself a finding about the gene and the disease.
autoimmune disease (18 papers, 2011 to 2025). A disorder resulting from loss of function or tissue destruction of an organ or multiple organs, arising from humoral or cellular immune responses of the individual to their own tissue constituents. "To prioritize autoimmune diseases risk variants with potential regulatory function on IRF8 expression, we developed a strategy to screen the genetic variants with CRISPRa assay using gRNAs targeting the SNP-containing region." (PMID 35388006, 2022). "EMC8 and COX4I1 RNA expression was relatively unchanged by activation, whereas IRF8 expression was upregulated 97-fold, coincident with the induction of 16 intergenic IRF8 PIRs, four of which overlap autoimmune disease fine-mapped variants." (PMID 28870212, 2017). "Aberrant methylation change of IRF8 confers risk to various tumors, and abnormal expression of IRF8 is involved in many autoimmune diseases, including ocular Behcet’s disease." (PMID 28432342, 2017). "Members of the Interferon Response Factor family of transcriptional regulators, IRF1 and IRF8, have been identified as genetic risk factors for several chronic inflammatory and autoimmune diseases." (PMID 24954358, 2014). "IRF8 gene variations have been linked to subclinical AS in patients with autoimmune diseases." (PMID 37727764, 2023). "By integrating genetic data and epigenomic analysis, we devised an approach to first rank all SNPs associated with autoimmune diseases in the IRF8 locus based on the presence of active enhancer marker and then identify candidate SNPs with potential regulatory function." (PMID 35388006, 2022). "Several genetic studies have nominated IRF8 as an important autoimmune disease risk gene." (PMID 35388006, 2022). "Despite the substantial heritability of the IRF8 locus, the functional variants, causative genes, and underlying gene regulatory mechanisms involved in autoimmune disease are largely unknown." (PMID 35388006, 2022). "Since the IRF8 locus has been shown to be directly bound by Vdr, the association found between rs2254210 and Irf8 plasma levels in our analysis further highlighted the functional link between the two proteins involved in autoimmune disease risk." (PMID 35888189, 2022). "Interestingly, we also observed associations between the IRF8 promoter locus and various other genomic regions, some of which contain autoimmune disease-associated genetic variants and the regulatory functions have been validated in CRISPRa screening assays." (PMID 35388006, 2022). "Moreover, accumulating evidence demonstrates that single nucleotide polymorphisms (SNPs) of IRF8 are associated with several autoimmune diseases, including BD." (PMID 28881647, 2017). "Moreover, IRF8 polymorphisms have been found to be involved in various autoimmune diseases, including ocular Behcet’s disease." (PMID 28432342, 2017). "Several studies have shown that IRF8 is associated with several autoimmune diseases, including BD." (PMID 28881647, 2017). "In support of a role for IRF8 in regulation of Th1-Th17 axis, patients with mutations in IRF8 have impaired Th1 responses and single nucleotide polymorphisms (SNPs) in Irf8 are associated with several autoimmune diseases in which IFN-γ+ Th17 cells play a pathogenic role." (PMID 25769610, 2015). "In addition, IRF8 has been associated with another autoimmune disease, multiple sclerosis, although the SNP associated with multiple sclerosis (rs17445836) was not present in our study." (PMID 21779181, 2011). "However, whether aberrant methylation of IRF8 is associated with autoimmune diseases remains unknown." (PMID 28432342, 2017). "IRF8 has also been reported to be involved in many autoimmune diseases, including Behcet's disease (BD)." (PMID 28881647, 2017). "Several modulatory factors in the TLR signaling pathway including IRF3, IRF7, IRF8, TRIM20, MYD88 and NF-κB1 have been associated with autoimmune disease." (PMID 26794091, 2016).
autoimmune disease (continued). "Single nucleotide polymorphisms in the genes for IRF5, IRF7 and IRF8 have also been associated with an increased risk for SLE and other autoimmune diseases." (PMID 23826184, 2013). "It is also a bit early to speculate on the role of methylation control of IRF8 in the clinical management of BD, although control of methylation might represent a future target in the treatment of this and other autoimmune diseases." (PMID 28881647, 2017). "IRF8, TMEM39A and IKZF3-ZPBP2 were previously identified as susceptibility loci for SLE in the multiracial replication study, Besides, ORMDL3 and GSDMB were found to have susceptibility loci for autoimmune diseases." (PMID 28427360, 2017). "Investigating the TFs regulating the fine‐mapped autoimmune disease enhancers, we find the known immune response TFs NFKB1/2, RELB and IRF8, but also MBD2, ZBT14 and PURA, which we identified as important TFs for predicting response to infection." (PMID 37073532, 2023). "In conclusion, the findings provided in this study point to a direct role of IRF8 in STING-mediated innate immune responses, which contributes to our understanding of the complicated mechanisms of autoimmune diseases and tumorigenesis." (PMID 35973990, 2022). "The role of epigenetic control of IRF8 in autoimmune disease has not been reported yet and our study is among the first to address this issue." (PMID 28881647, 2017).
atherosclerosis (16 papers, 2014 to 2025). A disease characterized by the build-up of fatty material and calcium deposition in the arterial wall resulting in partial or complete occlusion of the arterial lumen. "Of these, CXCL9, CXCL10, CCL5, CCL8, CRCL2, Cd74 and IRF8 have previously been implicated in atherosclerosis." (PMID 25478796, 2014). "IRF8 appears to play a complex, cell type-specific role in atherosclerosis development, with myeloid IRF8 promoting plaque formation." (PMID 40607379, 2025). "To provide targeted diagnostic assistance for atherosclerosis patients, we constructed a proprietary Nomogram model based on the expression of PLEK, IRF8, BTK, CCR1, and CD68." (PMID 38716195, 2024). "By high throughput RNA sequencing, loss-of-function experiment and SMC-lineage tracing technology, we identified SMC as the origin of SMC5 and demonstrated a regulating role of IRF8 in SMC transdifferentiation towards macrophage during atherosclerosis." (PMID 38389849, 2024). "Together, these results demonstrated that IRF8-NF-κb axis conferred a positive role in SMC transdifferentiation towards macrophage during atherosclerosis." (PMID 38389849, 2024). "We assume that the diminished cAMP content coupled to the enhanced PU.1 and IRF8 expression in these cells translated into the antiinflammatory macrophage phenotype and reduced atherosclerosis in S1pr1-LysMCre and S1pr1-F4/80Cre mice." (PMID 39531328, 2024). "Previous studies have uncovered associations between immune-response genes (such as PD-L1, CD73, MHC-I, and IRF8) and human heart diseases including cardiomyopathy, atrial fibrillation, and atherosclerosis." (PMID 38012001, 2024). "On the other hand, IRF8, another transcriptome enriched in severe atherosclerosis, was previously shown to be an upstream mediator of LC3, leading to autophagosome formation." (PMID 38259450, 2023). "Deletion of Interferon Regulatory Factor 8 (IRF8) for example results in neutrophilia which exacerbates atherosclerosis in IRF8−/− ApoE−/− chimeric mice, but was at the same time accompanied by changes in monocytes and several dendritic cell populations." (PMID 31601924, 2019). "To further investigate the potential role of gut microbiota-associated core macrophage genes in atherosclerosis, we applied unsupervised clustering methods based on the expression of PLEK, IRF8, BTK, CCR1, and CD68 to classify atherosclerosis patients into groups A and B." (PMID 38716195, 2024). "Gut microbiota-associated macrophage genes (PLEK, IRF8, CD68, CCR1, and BTK) may be implicated in the pathogenesis of atherosclerotic plaques and could serve as diagnostic markers to aid patients with atherosclerosis." (PMID 38716195, 2024). "Leveraging machine learning algorithms, we have identified PLEK, IRF8, BTK, CCR1, and CD68 as evaluative markers to assist in the diagnosis of atherosclerosis." (PMID 38716195, 2024).
breast cancer (15 papers, 2017 to 2025). A primary or metastatic malignant neoplasm involving the breast. "In line with this, the MBD2 regulon was downregulated in response to infection but upregulated in breast cancer‐associated macrophages, showing the opposite pattern to the IRF8 regulon." (PMID 37073532, 2023). "The low expression of IRF8 in hepatocellular carcinoma and breast cancer has been associated with a low response to immune therapy (IFN-γ and ICIs)." (PMID 38288118, 2023). "Thus, β-catenin signaling was implicated in the anti-tumor effect of IRF8 in multiple cancers, including breast cancers." (PMID 28388578, 2017). "However, the promoter methylation status, functions and underlying mechanisms of IRF8 in breast cancer remain unclear." (PMID 28388578, 2017). "IRF8 acts as a candidate TSG in breast cancer, but its underlying mechanism remains unclear." (PMID 28388578, 2017). "In a recently published study, they reported that GCSF is an important tumor-related factor that can reduce the level of IRF8 in alveolar macrophages and promote the metastasis of breast cancer with lung metastases." (PMID 39409083, 2024). "High IRF8 expression in tumor cells is correlated with a better response to immunotherapy and chemotherapy in human breast cancer." (PMID 36672246, 2023). "The expression of IRF8 was downregulated or silenced in breast cancer cell lines and primary breast cancers due to promoter hypermethylation." (PMID 28388578, 2017). "Interferon regulatory factor-8 (IRF8) is also a negative regulator of MDSC expansion, as IRF8 overexpression was found to attenuate MDSC accumulation in breast cancer and enhanced the responsiveness to immunotherapy." (PMID 28193698, 2017). "This study showed that the IRF8 promoter was frequently hypermethylated in primary breast cancers, and IRF8 served as a main downstream factor in the IFN-γ/STAT1 signaling pathway, with a possible role in enhancing the anti-tumor effect of IFN-γ." (PMID 28388578, 2017). "We previously showed that IRF8 expression was inversely correlated with hypermethylation of its promoter region in various cancer cell types, including breast cancer cells." (PMID 28388578, 2017). "In this study, the IRF8 promoter was methylated in 49.12% (56/114) of breast cancers, which was slightly higher than in breast cancers in previous studies (36%, 5/14)." (PMID 28388578, 2017). "Overall, these results demonstrated that the IRF8 promoter was frequently hypermethylated in breast cancers, but this correlation needs further confirmation in a larger sample group." (PMID 28388578, 2017). "In this study, we demonstrated that IRF8 was downregulated in breast cancers, mainly as a result of promoter hypermethylation." (PMID 28388578, 2017). "We evaluated IRF8 expression in a panel of breast cancer cell lines and three normal breast tissue samples by RT-PCR." (PMID 28388578, 2017). "Among these patients, the IRF8 promoter was hypermethylated in 49.12% (56/114) of breast cancer tissues and 16.67% (2/12) of surgical-margin tissues." (PMID 28388578, 2017). "We found that IRF8 was downregulated in breast cancer cell lines and primary tumors, compared with normal breast tissues, mainly because of aberrant promoter methylation." (PMID 28388578, 2017). "However, the role and underlying mechanism of IRF8 in breast cancer remains unclear." (PMID 28388578, 2017). "Expression of IRF8 has been shown to be silenced or downregulated due to promoter hypermethylation in multiple cancers, including breast cancers." (PMID 28388578, 2017). "It has been demonstrated that IRF8 is frequently methylated in breast cancers." (PMID 28388578, 2017). "In conclusion, expression of the IFN-γ-inducible gene IRF8 may be downregulated due to promoter methylation, impairing its anti-tumor effect by modulating β-catenin signaling in breast cancers." (PMID 28388578, 2017).
breast cancer (continued). "In addition, IRF8 expression was downregulated in primary breast cancers according to real-time PCR (n = 12, p = 0.0241), compared with adjacent non-cancerous tissues (n = 7)." (PMID 28388578, 2017). "Although some evidence suggests that IRF8 enhanced cell proliferation, motility and invasion via TGF-β signaling, its function and underlying mechanism in breast cancer remain unclear." (PMID 28388578, 2017). "Furthermore, IRF8 acted as a candidate TSG in breast cancer, at least partly by suppressing the β-catenin signaling pathway." (PMID 28388578, 2017). "Furthermore, the negative correlation between IRF8 promoter methylation and its transcriptional level also suggests that IRF8 might act as a tumor suppressor suppressing promoter methylation in breast cancer." (PMID 28388578, 2017). "However, IRF8, as a transcription factor, may thus modify other signaling pathways, such as β-catenin signaling in breast cancers." (PMID 28388578, 2017). "Among the breast cancers, the breast cancer cells recruit MDSC using cytokines and chemokines via three pathways, STAT3/IRF-8, PTEN/Akt and STAT3-NF-κB-IDO, to suppress anti-tumor immune responses and facilitate cancer cell proliferation." (PMID 36439106, 2022). "Our study demonstrates that high levels of IRF8 represent a favorable prognostic indicator in ER-negative (HER2+ and TNBC) breast cancer." (PMID 33766090, 2021). "Our analysis revealed a positive correlation between CSF-2 (GM-CSF) and IRF8, BATF3, or CCR7 in both lung and breast cancer patient cohorts." (PMID 32759497, 2020). "Previous work in our laboratory has demonstrated that IRF8 expression is reduced in both MDSC subsets and their progenitors in mouse models of mammary carcinoma." (PMID 32983128, 2020). "We therefore determined the IRF8 promoter methylation status by MSP and analyzed the correlation between methylation status and clinicopathological features in primary breast cancer samples (n = 114) and surgical-margin tissues (n = 12)." (PMID 28388578, 2017). "We also evaluated the expression and promoter methylation of IRF8 in 7 paired breast cancer tissues and matched non-cancerous adjacent tissues." (PMID 28388578, 2017). "The lung-metastatic potency of tumor cells was previously shown to be enhanced when IRF8 function was disrupted in BALB/c mice, indicating that downregulation of IRF8 expression may contribute to breast cancer cell migration and invasion." (PMID 28388578, 2017). "We also showed that IRF8 may act as a candidate TSG by inducing cell cycle arrest and apoptosis, and inhibiting cell migration and invasion in breast cancer by inhibiting β-catenin signaling." (PMID 28388578, 2017). "In addition, Irf8 expression is down-regulated in MDSC during tumor growth and the frequency of MDSC in patients with breast cancer correlates inversely with IRF-8 levels in these cells." (PMID 28968468, 2017). "Moreover, the percentage of apoptotic cells was significantly increased in IRF8-transfected breast cancer cells by cleaving PARP, indicating the pro-apoptotic effect of IRF8." (PMID 28388578, 2017). "Consequently, CD8+ T-cell effector (Teff) score, comprising gene expression of IFNG, PRF1, CD8A and CD8B, and BATF3-DC score, calculated with the expression level of BATF3, IRF8, THBD, CLEC9A, and XCR118 were markedly increased in the high SLAMF6 group than in the low SL AMF6 group in breast cancer." (PMID 38287061, 2024). "Similarly, there was a negative correlation between IRF8 promoter methylation and its expression in TCGA breast cancer database (n = 549, r = −0.1709, p < 0.0001)." (PMID 28388578, 2017). "Furthermore, a negative correlation between the expression of IRF8 and the abundance of the immature CD33+HLA-DR− MDSC subset in breast cancer patients substantiated the important role of IRF8 as a negative regulator of PMN-MDSC levels originally observed in mouse tumor models." (PMID 32983128, 2020).
chronic myeloid leukemia (15 papers, 2011 to 2025). "IRF8-deficient macrophages from chronic myelogenous leukemia-prone mice exhibit reduced CD36 expression, impairing efferocytosis of apoptotic polymorphonuclear neutrophilic leukocytes (PMNs)." (PMID 40980176, 2025). "Recently there has been increasing evidence for an association between IRF8 and dendritic cell deficiencies leading to diseases such as chronic myelogenous leukemia, atherosclerosis, and cancers." (PMID 36078039, 2022). "IRF8-deficient mice are characterized by a myeloproliferative phenotype resulting in a syndrome similar to human chronic myelogenous leukemia." (PMID 21261980, 2011). "Furthermore, in chronic myelogenous leukemia-prone mice, IRF8 is implicated in regulating phagocytic function of macrophages." (PMID 40980176, 2025). "Additionally, research has demonstrated that IRF8 deficiency, coupled with activated β-catenin, contributes to the progression and drug resistance of chronic myeloid leukemia." (PMID 39940857, 2025). "Indeed, IRF8 deficient mice developed a syndrome resembling human chronic myelogenous leukemia." (PMID 31178872, 2019). "IRF8 has previously been described to function as a tumor suppressor in multiple cancer types, including chronic myeloid leukemia (CML) and murine acute promyelocytic leukemia (APL), a subclass of AML." (PMID 33673123, 2021). "In chronic myeloid leukemia SNPs in ARHGAP26 and IRF8 showed significant association with an increased risk of CML, however only for the uncorrected p-value." (PMID 24886876, 2014). "In contrast, IRF8-null mice show noticeable clonal expansion of undifferentiated granulocytes and macrophages, which often progress to a chronic myelogenous leukemia (CML) like syndrome in these animals." (PMID 23658517, 2013). "Furthermore, IRF8 is transcriptionally repressed in many acute and chronic myeloid leukemia (AML and CML, respectively) patients, suggesting a link between IRF8 activity and these diseases." (PMID 25615614, 2015). "Moreover, IRF8 expression was extremely low or undetectable in 79% of chronic myelogeneous leukemia (CML) patients and 66% of acute myeloid leukemia (AML) patients." (PMID 23658517, 2013). "Furthermore, we demonstrate that Irf8-/-Irf4-/- mice exhibit a more severe chronic myeloid leukemia (CML)-like disease than Irf8-/- mice, involving a disproportionate expansion of granulocytes at the expense of monocytes/macrophages." (PMID 22003407, 2011). "Importantly, mice lacking the Irf8 gene (Irf8-/- mice) develop a chronic myelogenous leukemia (CML)-like syndrome, in which there is a disproportionate expansion of neutrophils at the expense of monocytes/macrophages." (PMID 22003407, 2011).